GUSB (glucuronidase beta)
Description:
Plays an important role in the degradation of dermatan and keratan sulfates.
Synonyms: BG; MPS7
Tractability: Small molecule: a structure with a bound ligand is known; a high-quality ligand is known; it has a high-quality binding pocket. Antibody: its Gene Ontology location is reachable by antibodies, with high confidence; UniProt predicts a signal peptide or a membrane-spanning region. PROTAC: ubiquitination databases record sites on it; its protein half-life has been measured; a small molecule that binds it is known.
Target class: Enzyme; Hydrolase
Gene: Protein-coding gene on chromosome 7 (65,960,677 to 65,982,283, reverse strand). Ensembl gene ENSG00000169919.
Subcellular location: Lysosome
Subcellular location (Human Protein Atlas): Vesicles
Pathways (Reactome):
Disease: MPS VII - Sly syndrome (CS/DS degradation); MPS VII - Sly syndrome (Hyaluronan metabolism)
Metabolism: CS/DS degradation; Hyaluronan degradation
Immune System: Neutrophil degranulation
Gene Ontology:
Molecular function: beta-glucuronidase activity; protein domain specific binding; signaling receptor binding; carbohydrate binding; hydrolase activity; hydrolase activity, hydrolyzing O-glycosyl compounds
Biological process: hyaluronan catabolic process; carbohydrate metabolic process; chondroitin sulfate proteoglycan catabolic process; glycosaminoglycan catabolic process; heparan sulfate proteoglycan catabolic process
Cellular component: extracellular exosome; extracellular region; membrane; azurophil granule lumen; ficolin-1-rich granule lumen; lysosomal lumen; endoplasmic reticulum; lysosome
Genetic constraint (gnomAD): Loss-of-function variants: 47 observed, 68.79 expected, observed/expected ratio (o/e) 0.68, 90% interval 0.54 to 0.87. The upper end of that interval is the gene's LOEUF score, 0.87, which puts it in group 3 of 6, group 1 being the genes least tolerant of losing a copy. Missense variants: 714 observed, 828.35 expected, observed/expected ratio (o/e) 0.86, 90% interval 0.81 to 0.92. Synonymous variants: 345 observed, 340.35 expected, observed/expected ratio (o/e) 1.01, 90% interval 0.93 to 1.11.
Gene-disease validity (ClinGen):
ClinGen rates the evidence that GUSB causes each of these diseases.
mucopolysaccharidosis type 7 (autosomal recessive): Definitive. Mucopolysaccharidosis type VII (MPS VII) is a very rare lysosomal storage disease belonging to the group of mucopolysaccharidoses.
Homologues: Orthologues: chimpanzee GUSB (99% identical), chimpanzee GUSB (95% identical), macaque GUSB (94% identical), pig GUSB (82% identical), dog GUSB (81% identical), rabbit GUSB (80% identical), guinea pig GUSB (79% identical), mouse Gusb (74% identical), rat Gusb (73% identical), zebrafish gusb (64% identical), tropical clawed frog gusb (64% identical), Drosophila melanogaster CG15117 (44% identical), and 2 more. Paralogues in human: MANBA (20% identical).
Diseases named in the same sentence as GUSB in open-access papers:
GUSB is named in the same sentence as 86 diseases in open-access papers, as found by Europe PMC text mining. Sharing a sentence is not in itself a finding about the gene and the disease. The quoted sentences say what the papers report.
mucopolysaccharidosis type 7 (21 papers, 2011 to 2025). "These include SMPD1 (Niemann–Pick A), NEU1 (sialidosis), NAGLU (Sanfilippo B), GUSB (mucopolysaccharidosis VII), GRN, which dominantly causes frontotemporal dementia, and GALC." (PMID 40391866, 2025). "Mutations in GUSB gene lead to mucopolysaccharidosis type VII (MPS VII, Sly disease), a lysosomal storage disease inherited in an autosomal recessive manner." (PMID 39404425, 2024). "MPSVII (Sly Syndrome) is caused by the deficiency of β-glucuronidase (GUSB) and has both neurological and multisystem involvement." (PMID 36172050, 2022). "In nine cases, WES helped to identify a monogenetic genetic disease; for example, in two unrelated cases, pathogenetic variants in the GUSB gene were identified, leading to the diagnosis of mucopolysaccharidosis type 7." (PMID 35160154, 2022). "Mucopolysaccharidosis VII (or Sly syndrome) is an autosomal recessive disorder characterised by a deficiency in the enzyme Beta-glucuronidase (GUSB)." (PMID 36299251, 2022). "MPS was suspected; levels of β-glucuronidase activity were low (0.6 nmol/h/mg protein) and genetic testing found a homozygous mutation in exon 3 of the GUSB gene, confirming Sly syndrome when he was 26 months old." (PMID 34686181, 2021). "Mucopolysaccharidosis type VII, or Sly syndrome, is caused by β-glucoronidase(GUSB) deficiency, resulting in lysosomal build-up of chondroitin, dermatan andheparan sulfate." (PMID 31132295, 2019). "These mutations predict GUSB-related mucopolysaccharidosis VII, another established cause of NIHF in severe cases." (PMID 26036949, 2015). "The GUSB mutation defines this canine skeletal syndrome as a mucopolysaccharidosis VII, a lysosomal storage disease affecting mainly connective tissue." (PMID 22815736, 2012). "GUSB defects cause mucopolysaccharidosis VII (MPS VII) in several species and define the skeletal syndrome in Brazilian Terriers." (PMID 22815736, 2012). "Finally, mucopolysaccharidosis type VII and type IX are caused by mutations in genes encoding the enzymes beta-glucuronidase (GUSB) and hyaluronoglucosaminidase-1 (HYAL1), respectively." (PMID 38425718, 2024). "Similarly, exon creation due to insertion of an Alu element has been observed in the β-glucuronidase gene (GUSB) that causes Sly syndrome or mucopolysaccharidosis type VII." (PMID 35269693, 2022). "And GUSB deficiency could cause mucopolysaccharidosis VII (MPS VII)." (PMID 35127693, 2021). "Pt3 was heterozygous for the known pathogenic variant c.1874_1875del, p.(Arg625Ilefs*7) in the beta‐glucuronidase (GUSB) gene, which is altered in mucopolysaccharidosis VII." (PMID 40391866, 2025). "Sly disease, or MPS type VII, is an autosomal recessive LSD caused by mutations in the human GUSB gene, which encodes the β-Glucuronidase enzyme." (PMID 41511290, 2025). "Mucopolysaccharidosis type VII [OMIM:253220], also called Sly syndrome, is an ultra-rare AR LSD caused by mutations affecting the gene encoding beta-glucuronidase (GUSB) located on chromosome 7q11." (PMID 37239976, 2023). "Mucopolysaccharidosis type VII (Sly disease, MPS VII), is an ultra-rare autosomal recessive, lysosomal storage disorder caused by deficiency of the enzyme β-glucuronidase (GUSB)." (PMID 31727109, 2019). "The in vivo efficacy of THLs was investigated in a model of type VII mucopolysaccharidosis (MPS), which is caused by mutations in the gene encoding the lysosomal enzyme β-glucuronidase (GUSB)." (PMID 22175028, 2011). "Finally, Sly disease, also known as MPS VII, is caused by mutations in the GUSB gene, resulting in β-Glucuronidase (GUSB) enzyme deficiency." (PMID 41511290, 2025). "Mucopolysaccharidosis type VII (MPS VII), also known as Sly syndrome, is a progressive neurometabolic disorder caused by a congenital deficiency of the lysosomal enzyme β-glucuronidase (GUSB)." (PMID 34686181, 2021).
breast carcinoma (10 papers, 2007 to 2025). "Emerging evidence also suggests that GUSB activity may correlate with musculoskeletal health in post-menopausal breast cancer survivors, a population that, as with RA sufferers, suffers from accelerated frailty and also reports a high prevalence of turmeric use." (PMID 40278395, 2025). "In addition, GUSB, TUBA1A, RPL13A, and B2M, which previous studies suggested being stable RGs in breast cancer research, and two classical RGs, ACTB and GAPDH, were also considered." (PMID 34895237, 2021).
Sepsis (4 papers, 2019 to 2023). Sepsis is defined as life-threatening organ dysfunction caused by a dysregulated host response to infection. "A different study also confirmed increased GUSB in adult ICU sepsis patients." (PMID 37533854, 2023). "Of note, although GUSB has been used as a housekeeping gene in expression studies, we and others show that it can function as a measure of disease severity for influenza and sepsis." (PMID 37533854, 2023). "This would be consistent with the elevated expression of the validated endo-lysosomal DEGs GUSB and HEXA (azurophilic granules) as well as LAIR1 (specific granules) in high-density blood neutrophils from ICU patients with sepsis." (PMID 35844509, 2022). "Any of the three and/or the pooled sepsis groups significantly differed from the ICU controls for a total of eleven genes, including higher sepsis levels for the endo-lysosomal genes DIAPH2, GUSB, HEXA, LAIR1, and SGSH." (PMID 35844509, 2022). "Invariant expression of our five candidate genes selected for NK cells and additionally of the known endogenous reference gene GUSB was confirmed in a subset of SIRS and sepsis samples from the discovery set by RT-PCR." (PMID 31075840, 2019).
lysosomal storage disease (3 papers, 2012 to 2025). A metabolic disorder caused by mutations in proteins critical for lysosomal function, including lysosomal enzymes, lysosomal integral membrane proteins, and proteins involved in the post-translational modification and trafficking of lysosomal proteins. "Pseudodeficiency variants were also identified in other lysosomal storage disorders, such as p.R247W and p.R249W in the HEXA gene, p.A300T in the IDUA gene, p.R595W in the GLB1 gene, p.D152N in the GUSB gene, and p.D313Y in the GLA gene." (PMID 40449593, 2025).
mucopolysaccharidosis (3 papers, 2017 to 2025). A group of autosomal recessive or X-linked inherited lysosomal storage disorders affecting the metabolism of mucopolysaccharides, resulting in the accumulation of mucopolysaccharides in the body. "GUSB gene mutations are reportedly associated with mucopolysaccharidosis (MPS) type VII, an autosomal recessive disease." (PMID 39830021, 2025). "Furthermore, germline mutations of GUSB gene cause autosomal recessive disorder, mucopolysaccharidoses, characterized with production of excessive mucus." (PMID 28426742, 2017).
Alzheimer disease (2 papers, 2014 to 2025). A progressive, neurodegenerative disease characterized by loss of function and death of nerve cells in several areas of the brain leading to loss of cognitive function such as memory and language. "Other studies have suggested increased expression of the GUSB gene for certain diseases, such as inflammatory and liver diseases and some types of cancer, and as a biomarker for changes in memory in Alzheimer’s disease." (PMID 40275366, 2025). "Due to high stability, GUSB was noted as a suitable RG in lung and ovarian cancers, whereas RPL13 was the best RG in Alzheimer’s disease and in mesenchymal stem cell study." (PMID 25225161, 2014).
bladder cancer (2 papers, 2008 to 2020). "Mean CT and mean AE for the 46 bladder cancer related genes and the endogenous control GUSB obtained before and after cDNA preamplification." (PMID 18710479, 2008). "As they consistently ranked in the top ten by CoV, GeNorm and Normfinder, UBC, RPLP0, HMBS, GUSB, and TBP are the most suitable endogenous control genes for bladder cancer qPCR." (PMID 33057113, 2020).
Cognitive impairment (2 papers, 2020 to 2022). Abnormal cognition is characterized by deficits in thinking, reasoning, or remembering. "Moreover, proteins associated with cognitive impairments, like GRN, ARSA, NCAM1, and GUSB, also showed marked differences in protein levels." (PMID 32850779, 2020).
colon cancer (2 papers, 2016). "Next, we examined the change in PKC coding genes in colon cancer tissue when the data was normalised to one RG, PGK1, and normalised to three RGs, PGK1, GUSB and PP1A." (PMID 26962435, 2016).
COVID-19 (2 papers, 2022). A disease caused by infection with severe acute respiratory syndrome coronavirus 2. "As a result, GUSB can play a central role in COVID-19 progression." (PMID 35887528, 2022). "CDC25A, GUSB, MYBL2, and SDAD1 were identified as key genes in severe COVID-19." (PMID 35887528, 2022).
diabetes (2 papers, 2024 to 2025). "Among other more-expressed proteins in patients with diabetes are CES1, GDF15, and GUSB proteins, which were previously associated to T2D." (PMID 38732002, 2024).
hepatocellular carcinoma (2 papers, 2022 to 2025). A malignant tumor that arises from hepatocytes. "The overexpression of GUSB has been reported to cause primary resistance to immunotherapy in hepatocellular carcinoma, suggesting a novel strategy for enhancing the efficacy of anti‐PD‐1 therapy." (PMID 39830021, 2025). "Seventeen glycolysis‐related genes (GRGs), including GUSB, were found to be dramatically progressive factors in patients with hepatocellular carcinoma." (PMID 39830021, 2025).
hydrops fetalis (2 papers, 2020 to 2025). Hydrops fetalis is a severe and challenging fetal condition usually defined as the excessive accumulation of fetal fluid within the fetal extravascular compartments and body cavities that manifests as edema, pleural and pericardial effusion and ascites. "The patient, who initially presented with hydrops fetalis and developmental delay, was diagnosed at age 4 through genetic analysis, which revealed compound heterozygous variants of c.104C > A (p.Ser35Ter) and c.1454C > T (p.Ser485Phe) on the GUSB gene." (PMID 40002615, 2025).
lung cancer (2 papers, 2024 to 2025). A malignant neoplasm involving the lung. "However, studies have shown that GAPDH, GUSB, and β-2 M were detected using qRT-PCR in 20 cases of lung cancer tissue and adjacent normal tissue, and the largest differences within and between groups were found in GAPDH." (PMID 38711158, 2024).
neuroblastoma (2 papers, 2009 to 2023). Neuroblastoma (NB) is the most common solid, extracranial childhood tumor. "Considering the lack of literature on reference genes for cfRNA, we pragmatically included GUSB, which is regularly used as a reference gene for the cellular compartment of peripheral blood for patients with neuroblastoma." (PMID 37046768, 2023). "In all 40 neuroblastoma samples, GUSB was detectable; for patients with localized disease, the mean was 38.2 copies/mL plasma (range 2.3–95 copies/mL plasma) and metastatic disease, 53 copies/mL plasma (range 10–220 copies/mL plasma)." (PMID 37046768, 2023). "mRNA expression levels of MYCN, ΔMYCN and MYCNOS were measured in 16 human neuroblastoma samples by QPCR relative to three reference genes: GUSB, TFRC and RNFIII." (PMID 19615087, 2009). "To study cfRNA in limited volume samples of pediatric patients with neuroblastoma, we first designed and optimized a multiplex ddPCR which included the neuroblastoma-specific targets PHOX2B, CHRNA3 and TH, and GUSB as a reference gene." (PMID 37046768, 2023).
Obesity (2 papers, 2024 to 2025). Accumulation of substantial excess body fat. "GUSB is involved in lysosomal degradation and has been implicated in inflammation and obesity-related metabolic dysfunction; its upregulation may signal hepatic stress or immune activation." (PMID 40502600, 2025). "Considering the network of proteins between control and obese groups, GUSB and CES1 are slightly more expressed in individuals with obesity, while significantly higher expression of both can be observed in T2D." (PMID 38732002, 2024).
soft tissue sarcoma (2 papers, 2017 to 2024). A malignant neoplasm arising from muscle tissue, adipose tissue, blood vessels, fibrous tissue, or other supportive tissues excluding the bones. "Reference genes stably expressed in canine soft tissue sarcoma are β-Glucuronidase (GUSB) and proteasome subunit, beta type, 6 (PSMB6); while in canine mammary gland tumors were a combination of hypoxanthine-phosphoribosyl transferase, ATP-synthase subunit 5B, ribosomal protein L32 and ubiquitin." (PMID 29178874, 2017). "Additionally, GUSB and PSMB6 were found to be the most stably expressed reference genes in canine soft tissue sarcomas, as determined using geNorm." (PMID 39335311, 2024).
thyroid tumor (2 papers, 2019 to 2020). A benign or malignant neoplasm affecting the thyroid gland. "They declared consistency between the different algorithms of NormFinder, BestKeeper, and GeNorm because all three suggested GUSB and HPRT1 as the most stably expressed genes in all thyroid tumours." (PMID 33110161, 2020). "The three algorithms were in agreement in identifying GUSB and HPRT1 as the most stably expressed genes in all thyroid tumors investigated." (PMID 31645594, 2019).
adenoma (1 paper, 2022). A neoplasm arising from the epithelium. "The protein, GUSB, was positively correlated to upregulated blood degradation proteins in adenoma patients." (PMID 36369736, 2022).
Arthritis (1 paper, 2022). Inflammation of a joint. "Previously, we identified beta-glucuronidase (GUSB) on mouse chromosome 5 (Chr5) as a major regulator of B. burgdorferi arthritis-associated locus 2 (Bbaa2)." (PMID 35324997, 2022).
breast tumor (1 paper, 2011). "The expression of six HKs (TFRC, GUSB, GAPDH, ACTB, HPRT1 and RPLP0) was investigated using geNorm and NormFinder softwares in forty breast tumor, four normal and eight adjacent tissues." (PMID 21702980, 2011).
cervical cancer (1 paper, 2021). A primary or metastatic malignant neoplasm involving the cervix. "GUSB participates in molecular pathways such as the innate immune system and can be used as a biomarker to predict lymph node metastasis in patients with early cervical cancer." (PMID 34630418, 2021).
cognitive decline (1 paper, 2022). "The bioinformatics data together indicate that upregulation of SERPINA1, VCP, PRNP, CIP2A, HSPA9, and UQCRC2 and downregulation of IGFBP3, CRHBP, PEPD, and GUSB were correlated to cognitive decline in T2DM patients." (PMID 36506101, 2022).
colon adenocarcinoma (1 paper, 2016). "Interestingly, even the isogenic cell lines SW480 (primary colon adenocarcinoma) and SW620 (its lymph node metastasis) significantly differed by SDHA and GUSB expression." (PMID 27339468, 2016).
endometrial cancer (1 paper, 2014). Primary or metastatic malignant neoplasm involving the endometrium (mucous membrane that lines the endometrial cavity). "Thus, according to the statistical analysis performed on the expression level of the 10 selected reference genes, GUSB, HPRT1 and PPIA were the best candidate for normalization purposes in gene expression studies in endometrial cancer versus normal tissue." (PMID 25473950, 2014).
glioma (1 paper, 2025). A benign or malignant brain and spinal cord tumor that arises from glial cells (astrocytes, oligodendrocytes, ependymal cells). "Inspired by this, a glucose metabolism‐related gene (GMG)‐based model, including LDHA, GUSB, GLB1, GALM, and FBP1, was proposed based on protein‒protein interaction analysis to predict the prognosis of patients with glioma." (PMID 39830021, 2025).
head and neck cancer (1 paper, 2017). A primary or metastatic malignant neoplasm affecting the head and neck. "While in both non-small lung cancer cell lines - A549 and NCI-H226, GUSB was the least variable gene; for the head and neck cancer cell lines - SCC6 and SC1483, HPRT1 and PP1A, respectively showed the smallest variation." (PMID 28262749, 2017). "Data analysis and ranking of the top 5 HKGs using geNorm and Normfinder identified UBC, TBP, IPO8, TFRC, GAPDH in head and neck cancer; TBP, IPO8, GUSB, UBC in lung and TBP, IPO8, TFRC, GUSB, HMBS in pancreas to be stable." (PMID 28262749, 2017). "In addition to these two genes, Ubiquitin C (UBC) in head and neck cancer and Transferrin receptor (TFRC) and β-Glucuronidase (GUSB) in pancreatic cancer were identified to be stable as well." (PMID 28262749, 2017).